APC (APC regulator of Wnt signaling pathway)
Diseases named in the same sentence as APC in open-access papers (continued):
Sharing a sentence is not in itself a finding about the gene and the disease.
tumor (continued). "The HRM set-up was tested on polyp-derived DNA of two apparently sporadic polyposis patients of whom tumor tissue was available (patients 13 and 14), and in whom no pathogenic APC variants in leukocyte-derived DNA were detected by HRM." (PMID 25604157, 2015). "As expected, loss of heterozygosity (LOH) of the APC gene was not present and was consistent with the benign nature of the hamartomatous tumor." (PMID 26141168, 2015). "Taken together, these results indicate that the tumor suppressive action of DKK-1 in DLD-1 cells in which the Wnt/β-catenin pathway is endogenously activated due to APC mutation is independent of Wnt." (PMID 25788273, 2015). "Given our results in C. elegans, we wondered whether human tumour cells require CDK4/6-cyclin D activity to counteract APC/CFZR1." (PMID 25562820, 2015). "Tumour suppressor APC was found in immunoprecipitated complexes as well." (PMID 25864732, 2015). "Whether the cellular released APC in tumor milieu can function in cell communication is another fascinating topic to be further addressed." (PMID 24977433, 2014). "However, in the case of colon cancers with known deletions in the APC (adenomatous polyposis coli) tumor suppressor gene, PPARγ agonists appear to promote tumor growth, and increase the number of colon polyps, possibly by increasing the uptake of dietary fat." (PMID 24672773, 2014). "Fourth, APC requires ‘two hits’ to inactivate its tumour suppressor activity." (PMID 24416237, 2014). "Although the same APC or β-Catenin mutations are present in all tumor cells of a CC, the WNT pathway is not uniformly active in these tumors." (PMID 24930890, 2014). "While DLD1 and SW480 cells both express a mutated form of APC, they differ with respect to the underlying genetic disturbance: DLD1 cells show microsatellite instability (MSI), whereas SW480 cells are derived from a tumor with chromosomal instability (CIN)." (PMID 24467841, 2014). "For three patients, the repeating somatic change was distant from codon 1307, suggesting there is no major repeating influence from the APC*I1307K mutation among synchronous tumours." (PMID 24416237, 2014). "Some of their tumours had been evaluated only for APC LOH and c.3924_3925insA." (PMID 24416237, 2014). "They focused on APC, a tumour suppressor gene that is often found to contain nonsense mutations in colorectal cancer tumours." (PMID 25205670, 2014). "For a more detailed analysis, we have expanded the region of the APC gene studied in these tumours." (PMID 24416237, 2014).
tumor (continued). "Finding that many different B-Raf mutations are allowed to occur in colorectal cancer (as well as the fact that APC mutation dominates) is consistent with findings that B-RafV600E inhibitors are generally not therapeutically useful in this tumour type." (PMID 24806839, 2014). "Collectively, these findings suggest that APC inactivation in tumor cells may elicit widespread changes in cytoskeletal dynamics and integrin signaling to modify tumor cell behavior." (PMID 23302090, 2013). "The expression level of SATB1 showed correlation with tumor differentiation and pTNM stage, and SATB1 was also associated with the expression of various biologic markers (including Cyclin D1, MMP-2, NF-κB, PCNA, APC and BRAFV600E)." (PMID 23326301, 2013). "As APC is an important tumour suppressor binding β-catenin, we then tested if berberine might affect the level of APC." (PMID 24015932, 2013). "The APC gene is a tumour suppressor gene that is involved in the control of β-catenin." (PMID 24148210, 2013). "In half of the sporadic cases of CRC in which no changes in APC occur, tumour development is associated with heterozygote mutations in the β-catenin gene (CTNNB1)." (PMID 24148210, 2013). "Collectively, these data suggest that both APC and intact microtubules are required for β-catenin localization at protrusion ends, the spindle-shaped, mesenchymal morphology and membrane protrusions that are important for tumor cell migration." (PMID 23302090, 2013). "The APC tumor suppressor gene is involved in APC/β-catenin/Tcf pathway." (PMID 23965959, 2013). "APC is a tumour suppressor gene and an important regulator of the Wnt signalling pathway." (PMID 24194897, 2013). "Therefore, the interaction with CTNNB1 has been considered to be essential for the tumor suppressor activity of APC." (PMID 23405266, 2013). "Enterotoxigenic bacteroides fragilis (ETBF), a human colonic commensal bacterium, can promote colonic tumorigenesis in APC mutant mice via Stat3 activation and Th17-cell polarization, and further blocking IL-17 or IL-23R can significantly reduce tumor formation in vivo." (PMID 24382972, 2013). "APC is a tumor suppressor gene, and inactivation of it leads to neoplastic tumor growth." (PMID 23737765, 2013). "Why is truncated APC required for tumour development in humans?" (PMID 22509309, 2012). "The present study predicts that for prevention of mitotic slippage, concomitant inhibition of APC/C-Cdh1 may be effective for tumor therapy with mitotic spindle poisons in humans." (PMID 22321970, 2012). "Patched Homolog 1 (PTCH1) is the SHH receptor and is the most commonly mutated tumor suppressor in BCC, whereas adenomatous polyposis coli (APC), secreted frizzled-related protein 1 (SFRP1), SFRP2, SFRP4, and SFRP5 are all negative regulators of the canonical WNT pathway." (PMID 23284750, 2012). "It is therefore likely that a germ-line APC whole gene deletion is followed by a mutation in the MCR of the second allele, a hypothesis which is also supported by our results indicating a requirement of truncated APC in tumour cells." (PMID 22509309, 2012). "Interestingly, the small intestine tumor incidence was significantly suppressed in ApcMin/+ mice carrying the transgene (hereafter referred to as Tg/APC)." (PMID 22876303, 2012). "For prevention of mitotic slippage, concomitant inhibition of APC/C-Cdh1 may be effective for tumor therapy with mitotic spindle poisons in human." (PMID 22321970, 2012). "For the prevention of mitotic slippage, concomitant inhibition of APC/C-Cdh1 may be effective for tumor therapy with mitotic spindle poisons in humans." (PMID 22321970, 2012). "The quantitative DNA methylation analysis of the candidate genes showed higher methylation proportion in the primary tumor tissue than that of the matched normal tissue and the differences were significant for the APC, BIN1, BMP6, BRCA1, CST6, ESR-b, P16, PTEN and TIMP3 promoter regions (P<0.05)." (PMID 22695536, 2012).
tumor (continued). "Downregulation of p68/p72 could also be one of the key factors that retard tumor development in the small intestine of Tg/APC." (PMID 22876303, 2012). "Alternatively, truncated APC might be required for tumour development independently of its control over the transcriptional activity of β-catenin, as previously discussed." (PMID 22509309, 2012). "However, the inverse correlation between methylation of p14 and APC with tumor recurrence needs to be further validated." (PMID 21599969, 2011). "As predicted by the APC germline mutations among these patients, a high percentage (29%) of FAP-associated desmoids showed loss of the APC region at 5q22.2, which was infrequently (3%) seen among sporadic tumours." (PMID 21931686, 2011). "In contrast, APC inactivation in progenitors or differentiated cells did not cause tumor formation even after 30 weeks." (PMID 24212796, 2011). "Out of the 27 tumours with LOH and one APC mutation, 15 had LOH of the wildtype allele based on the relative signal intensity of the mutated and wildtype alleles, 6 had LOH of the mutant allele and 6 cases could not be unequivocally resolved." (PMID 21901162, 2011). "LOH at the APC locus was found in 35 of 90 informative tumours (38.9%)." (PMID 21901162, 2011). "Patient 1 has tumor repressive transitions in the APC gene and tumor activating transitions in Axin, PP2A, β-catenin and in many downstream factors along the WNT-signalling pathway affecting transcription, cell cycle and CRC development, especially within the TCF/LEF family." (PMID 22011431, 2011). "The APC gene has long been recognized as a key tumor suppressor in sporadic and hereditary CC." (PMID 21694772, 2011). "Among the sporadic tumours, loss at 5q22.2 occurred only in the single case with a known somatic APC mutation (tumour D17), but not in the vast majority of cases carrying a β-catenin gene mutation." (PMID 21931686, 2011). "If and how these mechanisms may play a role in the tumor suppressor activity of APC remains to be determined." (PMID 21859464, 2011). "Surprisingly, methylation of p14 and APC were inversely correlated with tumor recurrence." (PMID 21599969, 2011). "LOH at the APC locus was found in 34.3% of tumours, MSI in 24.3% and MLH1 methylation in 12.7%." (PMID 21901162, 2011). "Moreover, other tumour suppressor genes, such as APC and Rb, also show similar differences between the frequency of single heterozygous mutations in vivo and in vitro." (PMID 21668955, 2011). "In our panel, most FAP-associated tumours harboured a documented germline APC mutation, whereas most non-FAP associated tumours carried a β-catenin gene mutation, confirming that these genetic changes are primary events in desmoid tumourigenesis." (PMID 21931686, 2011). "Besides, significant association between increased tumor grade, stage or tumor recurrence and methylation of p14, SFRP1, APC, hMLH1 and p15 were observed in samples from Hong Kong." (PMID 21599969, 2011). "In particular, inclusion of the APC gene in the small 5q22.1-q22.2 segment deleted in tumour P6A and its exclusion from the deleted 5q14.3-q22.1 segment in tumour D8 could be confirmed." (PMID 21931686, 2011). "The human tumor suppressor Adenomatous Polyposis Coli (APC) is a 2,843-residue protein." (PMID 21858148, 2011). "Interestingly, the CpG sites with strongest ability to discriminate tumor from surrounding tissue were found in the promoter of genes hypermethylated in HCC samples (e.g. APC, RASSF1A, CDKN2A, and FZD7)." (PMID 20305825, 2010). "Localised regulation of APC-phospho-β-catenin complexes may contribute to the tumour suppressor activity of APC." (PMID 21152425, 2010). "APC is illustrative of the multiple roles that certain tumor suppressors play in a cell." (PMID 20591184, 2010).
tumor (continued). "MSI-H colorectal cancers typically do not show mutations in neither APC, nor present with tumor buds." (PMID 21317460, 2010). "Moreover, studies have shown that normal adrenal as well as normal colonic mucosa in general shows APC promoter 1A methylation levels below 5%, as compared to the higher levels observed in the corresponding tumours." (PMID 20208994, 2010). "These are β-catenin-responsive genes: in the absence of epigenetic silencing, APC mutation and consequent β-catenin action would lead to Wnt antagonist induction in a negative feedback loop, starving the tumour cell of Wnt ligand." (PMID 20628379, 2010). "APC mutations are responsible for the autosomal dominant familial adenomatous polyposis (FAP) syndrome, and are also found in sporadic colorectal cancer as well as in other tumour types, such as cancer of the thyroid and mammary glands." (PMID 20208994, 2010). "To date, only one study investigating APC mutational status in four CNS PNET tumours has been reported, in which no mutations were found." (PMID 19293793, 2009). "Moreover, recent reports indicate that APC is an important prognostic indicator for unfavorable clinicopathological outcome and tumor recurrence in several types of cancers." (PMID 19149902, 2009). "This suggests that the extent of promoter methylation may directly reflect the promoter activity, perhaps is a fine mechanism in concert with other regulatory elements, as similarly observed in the tumor suppressor gene APC." (PMID 18452618, 2008). "The presence of proteins potentially involved in cell targeting and tumor antigen transportation in exosomes prompted us to hypothesize that tumor cell-derived exosomes could be antigen delivery systems allowing transfer tumor antigen from tumor cells to APC." (PMID 21892318, 2008). "These molecular characteristics of MAP carcinomas include: low MSI (Microsatellite instability), low frequencies of APC, β-cantenin mutations and LOH (Loss of Heterozygosity) of 18q, harboring the SMAD4 gene, and the karyotype of tumor cells typically being near-diploid." (PMID 19506731, 2008). "As a result, reduction in tumor cell growth can be achieved by either extracellular quenching of Wnts with monoclonal antibodies, β−catenin knockdown or restoring normal APC." (PMID 18382662, 2008). "To address the origins of the MCRA phenotype, we have determined the spectrum of somatic mutations at APC, K-ras and BRAF in tumours from 25 MCRA patients with no detectable germline mutation in APC, MYH or the MMR genes." (PMID 17505512, 2007). "Three out of the four tumors with β-catenin mutation were reported previously, and the one tumor without β-catenin mutation or the LRP5Δ666–809 transcript displayed wild-type APC expression." (PMID 18044981, 2007). "In both FAP and familial non-FAP tumours, mutations of the adenomatous polyposis coli (APC) gene on the long arm of chromosome 5 have been incriminated." (PMID 17343751, 2007). "Tumours from 464 of 656 patients, which did not harbour a truncating APC mutation or lacked hMLH1 expression, were analysed for mutations in exon 3 of the CTNNB1 gene." (PMID 16356174, 2005). "Nine percent of all tumours (58/656) lacked hMLH1 expression, and in these tumours almost no APC or K-ras mutations was detected." (PMID 16356174, 2005).
tumor (continued). "Furthermore, mice null for COX-2 in an APC mutant background (APCΔ716) develop 86% fewer tumours than mice with COX-2 expression." (PMID 12778076, 2003). "Fluorescent in situ hybridisation (FISH) analysis of tumour tissue from one patient exhibiting AI demonstrated two, three, four or six copies of the APC gene per cell, consistent with this hypothesis." (PMID 8980382, 1996). "Germline mutations of the tumour-suppressor gene APC, responsible for the predisposition to FAP, may therefore be involved in the pathogenesis of these tumours." (PMID 7981058, 1994). "Thus, we have identified a previously unknown APC/PTPN13/STAT1-dependent tumor immune-suppressive mechanism." (PMID 41486293, 2026). "This paradigm may explain many aspects of the natural history of tumour evolution, including the ubiquity of APC loss in CRC—whether APC loss occurs as a primary event or a secondary event, it can still enable tumour growth as a single ‘Big Bang’-type clonal expansion." (PMID 41339549, 2026). "Although a degree of variability in the fitness conferred by specific mutations of oncogenes is expected, for example, G12D variants compared with A146T in KRAS, that complete loss of the β-catenin–binding 20AARs in tumor-suppressive APC does not lead to maximal cancer risk is remarkable." (PMID 41091816, 2025). "Notably, this tumor exhibited genomic alterations and clinicopathological features that overlapped with both flat-type FGAs and FGPDs, despite the absence of an APC mutation." (PMID 39939466, 2025). "For example, miR-31 and miR-135b have both been implicated in the serrated neoplasia pathway—particularly in lesions with high microsatellite instability—high and BRAF mutations—whereas miR-143 and miR-145 are commonly associated with AD–carcinoma sequences and KRAS or APC mutations." (PMID 40693022, 2025). "Furthermore, research by Wei Wang and colleagues demonstrated that in ESCC, downregulation of the METTL3/YTHDF‐coupled epitope transcriptome via the APC gene negatively regulates the Wnt/β‐catenin pathway, thereby enhancing cell proliferation and tumor development." (PMID 39415846, 2024). "Thus, although the detailed molecular mechanisms may vary, further studies on MAPK-mediated APC/CCdc20 inhibition mechanism in human would lead to better understanding of its oncogenic role in tumor progression." (PMID 39412391, 2024).